JMJD4 (jumonji domain containing 4)
Description:
Catalyzes the 2-oxoglutarate and iron-dependent C4-lysyl hydroxylation of ETF1 at 'Lys-63' thereby promoting the translational termination efficiency of ETF1.
Synonyms: FLJ12517
Tractability: PROTAC: ubiquitination databases record sites on it.
Gene: Protein-coding gene on chromosome 1 (227,730,412 to 227,735,411, reverse strand). Ensembl gene ENSG00000081692.
Subcellular location: Cytoplasm
Subcellular location (Human Protein Atlas): Plasma membrane; Vesicles
Pathways (Reactome):
Metabolism of proteins: Protein hydroxylation
Gene Ontology:
Molecular function: 2-oxoglutarate-dependent dioxygenase activity; peptidyl-lysine 4-dioxygenase activity; protein binding; catalytic activity, acting on a protein
Biological process: positive regulation of translational termination; protein hydroxylation; peptidyl-lysine hydroxylation; regulation of gene expression
Cellular component: cytoplasm; cytosol
Genetic constraint (gnomAD): Loss-of-function variants: 34 observed, 33.69 expected, observed/expected ratio (o/e) 1.01, 90% interval 0.77 to 1.34. The upper end of that interval is the gene's LOEUF score, 1.34, which puts it in group 5 of 6, group 1 being the genes least tolerant of losing a copy. Missense variants: 584 observed, 545.57 expected, observed/expected ratio (o/e) 1.07, 90% interval 1 to 1.15. Synonymous variants: 269 observed, 224.88 expected, observed/expected ratio (o/e) 1.2, 90% interval 1.08 to 1.32.
Homologues: Orthologues: chimpanzee JMJD4 (99% identical), macaque JMJD4 (97% identical), rabbit JMJD4 (82% identical), dog JMJD4 (77% identical), rat Jmjd4 (77% identical), guinea pig JMJD4 (76% identical), pig JMJD4 (76% identical), mouse Jmjd4 (76% identical), tropical clawed frog jmjd4 (53% identical), zebrafish jmjd4 (52% identical), Drosophila melanogaster JMJD4 (35% identical), Caenorhabditis elegans jmjd-4 (28% identical). Paralogues in human: JMJD6 (21% identical), JMJD8 (16% identical).
Diseases named in the same sentence as JMJD4 in open-access papers:
JMJD4 is named in the same sentence as 18 diseases in open-access papers, as found by Europe PMC text mining. Sharing a sentence is not in itself a finding about the gene and the disease. The quoted sentences say what the papers report.
Clear Cell Renal Cell Carcinoma (2 papers, 2021 to 2023). "In the present study, we evaluated whether JMJD4 can be a prognostic marker of patients with clear cell renal cell carcinoma (ccRCC) using data from public platform and in vitro experiments." (PMID 34980950, 2021).
renal cell carcinoma (2 papers, 2021 to 2023). "Besides, in vitro experiments confirmed that high expression of JMJD4 can significantly promote the invasion ability (p < 0.001), cloning ability (p < 0.001), and proliferation (p < 0.001) of renal cell carcinoma." (PMID 34980950, 2021).
bladder cancer (1 paper, 2021). "The expression of JMJD4 was also higher in bladder cancer, breast cancer, cholangiocarcinoma, colon cancer, renal cancer, lung cancer, etc., than in normal tissue (p < 0.01 or p < 0.001)." (PMID 34980950, 2021).
colon cancer (1 paper, 2021). "Histone demethylase JMJD4 is a burgeoning tumor marker, which has been proven to be associated with colon cancer, but the role it plays in kidney cancer has not yet been investigated." (PMID 34980950, 2021). "Currently, only one study has reported that JMJD4 expression could be a prognostic indicator for patients with colon cancer." (PMID 34980950, 2021).
dilated cardiomyopathy (1 paper, 2024). Cardiomyopathy which is characterized by dilation and contractile dysfunction of the left and right ventricles. "Research has indicated that the hydroxylation of PKM2 by Jmjd4 can promote the degradation of PKM2 in cardiomyocytes and prevent dilated cardiomyopathy." (PMID 39338381, 2024).
heart failure (1 paper, 2025). Inability of the heart to pump blood at an adequate rate to meet tissue metabolic requirements. "In the absence of Jmjd4, PKM2 activity increases, leading to cardiac metabolic disorders and heart failure." (PMID 40513070, 2025).
Hepatic steatosis (1 paper, 2022). Steatosis is a term used to denote lipid accumulation within hepatocytes. "Together, we find that JMJD4-demethylated RIG-I at K18 and K146 is an essential mechanism to inhibit hepatic steatosis and carcinogenesis." (PMID 36333807, 2022). "Altogether, we conclude that hepatic steatosis is promoted by the constitutive methylated RIG-I at K18 and K146, while suppressed by JMJD4-mediated RIG-I demethylation." (PMID 36333807, 2022).
kidney cancer (1 paper, 2021). Primary or metastatic malignant neoplasm involving the kidney. "Furthermore, to clarify the effect of JMJD4 on kidney cancer, we transfected the pcDNA-3.1(+)-JMJD4 plasmid into Caki-1 cells and verified the overexpression by qRT-PCR and western blot." (PMID 34980950, 2021). "This study is aimed at evaluating the prognostic value of JMJD4 in kidney cancer." (PMID 34980950, 2021). "In summary, high JMJD4 expression may be a prognostic marker in patients with kidney cancer." (PMID 34980950, 2021). "However, the relationship between JMJD4 and tumor, especially kidney cancer, has not been reported yet." (PMID 34980950, 2021).
prostate carcinoma (1 paper, 2023). A carcinoma that arises from epithelial cells of the prostate gland. "Other six genes, including upregulated JARID2, JMJD4, and RIOX2, as well as downregulated HIF1AN, HR, and UTY were not reported in prostate cancers so far." (PMID 36776320, 2023).
renal carcinoma (1 paper, 2021). A carcinoma arising from the epithelium of the renal parenchyma or the renal pelvis. "To further evaluate the mechanism of high expression of JMJD4 in promoting the progression of renal cancer, we performed GO and KEGG analysis." (PMID 34980950, 2021). "Therefore, we investigate the relationship between JMJD4 and renal cancer." (PMID 34980950, 2021).
steatosis (1 paper, 2022). Increased lipid within the cytoplasm of cells. "More interestingly, JMJD4-demethylated RIG-I is beneficial in preventing both steatosis and inflammation-induced carcinogenesis, while the constitutive methylated RIG-I tends to promote them both, which are determined in RIG-I K18A+K146A mice and K18M+K146M mice in vivo." (PMID 36333807, 2022). "Mechanistically, constitutive methylated RIG-I at K18 and K146 enhances hepatic cholesterol synthesis and lipid accumulation, thus promoting steatosis and the following NASH and NASH-HCC, whereas JMJD4-demethylated RIG-I suppresses IL-6 response and inflammation-induced hepatocarcinogenesis." (PMID 36333807, 2022). "Moreover, as JMJD4 is responsible for the demethylation of RIG-I at K18 and K146, we confirmed that HFD-induced steatosis and STAM hepatocarcinogenesis were both promoted in Jmjd4hep−/− mice, which were similar to those in RIG-I K18M+K146M mutant mice." (PMID 36333807, 2022).
cancer (4 papers, 2016 to 2023). A tumor composed of atypical neoplastic, often pleomorphic cells that invade other tissues. "The results of box plot analysis demonstrate that high expression of JMJD4 is a common feature of multiple human cancers, including ccRCC." (PMID 34980950, 2021). "Our results demonstrated that JMJD4 may be a cancer-promoting gene, and high expression of JMJD4 portends a poor prognosis in these patients." (PMID 34980950, 2021). "In turn, overexpression of JMJD4 and FIBCD1 has been linked to cancers of the GI tract." (PMID 34151400, 2021). "The variants and expression bias of genes in this family are related to cancer regulations, thus the change made by MI in the JMJD4 gene may help enrich the study of JMJD4 and related cancer diagnosis." (PMID 26818118, 2016). "Jumonji-C domain-containing histone-demethylase 4 (JMJD4) is a newly discovered histone demethylase that has a role in carcinogenesis and its expression has been studied in many cancers, though it has not been sufficiently clarified in ccRCC." (PMID 37600577, 2023).
tumor (2 papers, 2021 to 2023). "Elevated levels of JMJD4 was positively correlated with big tumor mass (P=0.047), higher grades (P=0.003), higher stages (P=0.043), and distant spread (P=0.001)." (PMID 37600577, 2023). "High levels of NEK2 and JMJD4 were both related to tumor recurrence, and shorter RFS and OS rates (P<0.001)." (PMID 37600577, 2023). "Likewise, the high expression of JMJD4 showed positive correlation with the tumor size (P=0.047), higher grades (P=0.003), higher stages (P=0.043), distant spread (P=0.001), tumor recurrence, shorter PFS rate, and OS rate (P<0.001)." (PMID 37600577, 2023).
heart diseases (1 paper, 2023). "JMJD4 holds promise as a novel target for future therapeutic interventions in heart diseases and bears significant clinical translational value." (PMID 37759781, 2023). "Moreover, JMJD4 and BNP exhibit significant clinical translational value and may serve as critical therapeutic targets in future heart disease, deserving consideration in clinical practice." (PMID 37759781, 2023).
JMJD4 also shares sentences with these, for which no sentence is quoted: breast carcinoma (1 paper); cholangiocarcinoma (1); liver cancer (1); lung carcinoma (1).